TLR5 (toll like receptor 5)
Diseases named in the same sentence as TLR5 in open-access papers (continued):
Sharing a sentence is not in itself a finding about the gene and the disease.
tumor (continued). "Phosphor-autoradiography and biodistribution study showed that the uptake of 125I-anti-TLR5 mAb in TLR5+ 4T1 tumor was higher than that in TLR5− 4T1 tumor." (PMID 34336694, 2021). "For ex vivo imaging of isolated tumors, TLR5− 4T1 tumors showed much higher radioactivity accumulation than TLR5+ 4T1 tumors, and the fluorescence imaging obviously showed tumor in both groups." (PMID 34336694, 2021). "In the presence of skin microbes, elimination of several innate immune sensors, including TLR-5, protects from tumorigenesis, while inflammation correlates with tumor incidence." (PMID 33296049, 2021). "The radioactivity uptake of 125I-anti-TLR5 mAb in the tumor was much higher at 48 h than that at 24 h in both 4T1 TLR5+ and TLR5− tumors." (PMID 34336694, 2021). "We chose to target TLR5 since flagellin and its derivatives have been successfully used as vaccine adjuvants and have been shown to induce potent anti-viral and anti-tumor immune responses in animal studies and clinical trials." (PMID 33281829, 2020). "For instance, TLR-5 recognises bacterial flagellin, which can influence tumour growth and progression in vitro." (PMID 33008143, 2020). "Conversely, TLR5 agonist was reported that can induce an inflammatory response and inhibited some tumor progression." (PMID 33469538, 2020). "On the contrary, TLR5 stimulation in gastric cancer cells, notably by H. pylori, has been reported to increase IL-8 production, tumor cell proliferation as well as TNF-α expression levels that can support the suppressive effects of Treg cells." (PMID 33679703, 2020). "TLR5 signaling on cancer cells has been reported to inhibit tumor growth in various cancers, including breast cancer, head and neck cancer and colon cancer." (PMID 33679703, 2020). "In summary, various TLRs can be expressed on numerous cancer cell types and TLR3 and TLR5 appear to be the most promising adjuvants for combining direct anti-tumor properties with immunostimulant effects on APCs and T cells." (PMID 33679703, 2020). "The activation of TLR5 in human gastric cancers causes production of IL-8 and TNF-α, which lead to the proliferation of tumor cells." (PMID 32012718, 2020). "In previous studies employing multiple preclinical tumor models, we demonstrated that entolimod itself provokes a strong antitumor effect against TLR5-responsive tumors due to its immunostimulatory activity." (PMID 32027657, 2020). "To confirm that TLR5 affects tumor metastasis, we established lung metastasis mouse models by injecting TLR5+ 4T1 and TLR5− 4T1 cells via tail veins, and evaluated the findings using fluorescence imaging." (PMID 31852883, 2019). "Biodistribution assay showed that 125I‐anti‐TLR5 mAb was mainly metabolized through the liver and kidney, and 125I‐anti‐TLR5 mAb was much more accumulated in TLR5+ 4T1 tumour than TLR5− 4T1." (PMID 31576678, 2019). "We evaluated the ability of 4T1 cells to form tumors using colony formation assays to further determine the effects of TLR5 on tumor cell proliferation." (PMID 31852883, 2019). "Ex vivo biodistribution studies were performed to validate the imaging results and to further quantify the 125I‐antiTLR5 mAb uptake at 24, 48 and 72 hours in the TLR5+/− 4T1 tumour‐bearing model group." (PMID 31576678, 2019). "We therefore established a xeno-subcutaneous tumor model using nude mice, then monitored with an 125I-labeled anti-TLR5 mAb tracer, which was with high affinity for TLR5 in 4T1 cells in vitro." (PMID 31852883, 2019). "All other tissues (include TLR5− tumour) had a lower %ID/g, which was in agreement with the imaging data." (PMID 31576678, 2019). "Compared with 125I‐antiTLR5 mAb group,the T/NT ratio of 125I‐IgG group was only 2.023 ± 0.2149 at 48 hours in same TLR5+ 4T1 tumour, suggesting the non‐specific tumour binding of 125I‐IgG." (PMID 31576678, 2019). "High levels of TLR5 were expressed during intestinal epithelial cell-mediated anti-tumor activity in a mouse xenograft model of human colon cancer." (PMID 31852883, 2019).
tumor (continued). "The ratio of positively stained tumor cells was much higher for TLR5+ 4T1 than for TLR5− 4T1 tumors (n = 5; 68.75 ± 5.25% vs. 20.65 ± 5.65%, P < 0.01)." (PMID 31852883, 2019). "And more importantly, we found that the locations of fluorescence were tightly consisted with tracer radioactivity, which further proved that tumour image was TLR5 expression image specificity." (PMID 31576678, 2019). "More importantly, we found that locations of fluorescence emission contained more tracer radioactivity in TLR5+ 4T1 tumor, which further confirmed that tumor imaging was TLR5 expression-specific." (PMID 31852883, 2019). "Radioactivity DLU (digital light units)/mm2 of tumour area reached 121 042 ± 5587 cpm for TLR5+ 4T1 tumour, whereas only 34 245 ± 2747 cpm for TLR5− 4T1 tumour." (PMID 31576678, 2019). "In the block group, the 125I-anti-TLR5 mAb uptake of TLR5+ 4T1 tumor was only 1.67 ± 0.14 %ID/g at 48 h, suggesting that 125I-antiTLR5 binding with tumor was blocked by unlabeled anti-TLR5 mAb pre-injection in vivo." (PMID 31852883, 2019). "125I‐antiTLR5 mAb exhibited higher targeting efficiency in TLR5+ 4T1 tumours, compared with TLR5− 4T1 tumours." (PMID 31576678, 2019). "In this experiments, scientisits found that TLR4 signalling pathway is prerequisite in triggering the anti-tumour immune response and FlaB/TLR5 pathway augment this reaction." (PMID 31528208, 2019). "They concluded that flagellin-mediated TLR5 activation is involved in modulation of the tumour microenvironment and mediates its anti-tumorigenic effect through pro-inflammatory cytokine induction." (PMID 30692549, 2019). "Immunohistochemistry staining showed that TLR5 expression in tumours was indeed down‐regulated in TLR5− 4T1 mice." (PMID 31576678, 2019). "For isolated tumour ex vivo imaging, TLR5+ 4T1 tumours showed much higher uptake radioactivities than TLR5− 4T1 tumours." (PMID 31576678, 2019). "The surface and cytoplasm of tumor cells were immunohistochemically stained brown indicating TLR5 positivity." (PMID 31852883, 2019). "In vivo fluorescence imaging successfully showed tumour tissues clearly both in TLR5+ and TLR5− 4T1 mice compared with lentivirus untreated 4T1 tumour." (PMID 31576678, 2019). "Whole‐body phosphor‐autoradiography after 125I‐anti‐TLR5 mAb injection showed TLR5+ 4T1 tumour images in 24 hours, more clearly in 48 hours." (PMID 31576678, 2019). "Here, we monitored tumor locations using a TLR5 knockdown 4T1 cell line labeled with green fluorescent protein." (PMID 31852883, 2019). "For immunohistochemistry staining, the positive brown areas were found on the cell membrane and plasma, and the percentage of positive staining of TLR5+ is 69.75 ± 5.25%, much higher than that in TLR5− tumours (21.75 ± 3.15%), n = 5, ***P < .01." (PMID 31576678, 2019). "TLR5+ 4T1 tumours exhibited higher uptake, while TLR5− 4T1 tumours showed lower tumour uptake at all checking time‐points." (PMID 31576678, 2019). "The T/NT ratio of 125I‐antiTLR5 mAb group in TLR5− 4T1 tumours was significantly lower than in TLR5+ 4T1 tumours group, P < .05." (PMID 31576678, 2019). "In conclusion, the downregulation of TLR5 in TNBC increased tumor invasiveness and EMT expression and promoted TNBC metastasis." (PMID 31852883, 2019). "There is also evidence that stimulation through particular TLRs, such as TLR3 and TLR5, can induce anti-tumour responses and lead to increased tumour cell death." (PMID 29415982, 2018). "TLR4 and TLR5 stimulation reportedly activate cancer cell proliferation and promote tumor formation by various cancer cells." (PMID 30410674, 2018). "According to the study of Rutkowski and Conejo-Garcia TLR5 mediated recognition of commensal microbiota can modulate the systemic tumour-promoting inflammation and malignant progression due to the polymorphism of TLR5." (PMID 28715461, 2017).
tumor (continued). "In tumor-adjacent breast tissues, significant TLR5 expression was also detected in 89.3% breast duct epithelium cells, but not in the fibro-fatty tissue (n=28)." (PMID 29179462, 2017). "Larger epidemiological studies of ethnically diverse populations, as well as analysis of TLR5 expression in patient-matched tumor samples from the epidemiological study with survival information should be conducted in the future." (PMID 29179462, 2017). "Contrary to enhanced T cell-mediated antitumor responses, TLR5-dependent commensal bacteria promote tumor development by expanding MDSCs and dampen antitumor immunity in TLR5- and IL-6-dependent manner." (PMID 27965667, 2016). "It has been proven that toll-like receptor 5 (TLR5) plaied an important role in the development of tumor." (PMID 25603867, 2015). "Ablation of TLR-5 in radiosensitive leukocytes markedly reduced the number of tumours that developed on wounding." (PMID 25575023, 2015). "When flagellin was administered to wounds of TLR-5−/− BM chimeras, tumour formation was greatly diminished compared with control chimeras treated with flagellin." (PMID 25575023, 2015). "Antibiotic treatment inhibits, whereas injection of flagellin induces, tumours in a TLR-5-dependent manner." (PMID 25575023, 2015). "Our study shows that the microbiota, in a TLR5 signaling-dependent manner, drives the up-regulation of tumor-promoting IL-6 in the serum of tumor-bearing mice, subsequently promoting MDSC mobilization." (PMID 25897427, 2015). "Our studies indicate that in the context of chronic inflammation, TLR-5 signalling in leukocytes can tip the balance between normal wound repair and tumour formation." (PMID 25575023, 2015). "In contrast to the tumour-suppressive effects of TLR-5 ablation and antibiotic treatment, topical application of flagellin to InvEE wounds increased tumour incidence in a dose-dependent manner and delayed wound closure." (PMID 25575023, 2015). "Paradoxically, we have shown that acute stimulation of TLR5 with flagellin boosts anti-tumor immunity in established ovarian cancer models." (PMID 25897427, 2015). "There was a substantial delay in the development of DMBA/TPA-induced tumours in wounded TLR-5−/− BM chimeras relative to wounded WT chimeras." (PMID 25575023, 2015). "Taken together, these data demonstrate that exposure to bacterial flagellin sensed by TLR-5 on radiosensitive leukocytes promotes tumour formation in InvEE mice." (PMID 25575023, 2015). "The biodistribution study and autoradiography demonstrated that 131I-anti-TLR5 mAb was specifically retained in hepatocarcinoma with a high tumor uptake." (PMID 24932259, 2014). "Our previous report showed that the TLR5 agonist flagellin has a strong capacity to inhibit tumor growth." (PMID 24466264, 2014). "TLR5 signaling also exhibits radioprotective activity and improves the radiation efficacy of tumor cells in radiotherapy." (PMID 24466264, 2014). "Our findings demonstrate that CBLB502 stimulates tumor immunity via TLR5-expressing accessory immune cells which can then activate cytotoxic lymphocytes." (PMID 24454895, 2014). "It was found that H22-xenografted tumor tissue exhibited a higher level of TLR5 expression compared with normal liver tissues." (PMID 24932259, 2014). "During the first 12 h, a relatively high uptake of 131I-anti-TLR5 mAb was observed in the tumor site and in the blood, liver, kidney, spleen and lung." (PMID 24932259, 2014). "As shown in the imaging of autoradiography, it was found that 131I-anti-TLR5 became preferentially accumulated in the xenografted H22 tumor at 24 h, and then showed a gradual decline of uptake." (PMID 24932259, 2014). "Compared with the normal liver group, the groups of the H22 cell line and H22 xenograft tumor tissue exhibited higher levels of TLR5 mRNA expression (P<0.05)." (PMID 24932259, 2014). "Previous studies have reported that TLR5 activation can promote or inhibit tumor growth dependent on the tumor model." (PMID 24454895, 2014).
tumor (continued). "It is apparent that 131I-anti-TLR5 mAb localized at the site of the tumor to a significant extent at 24 h (ID/g reached ≤8.26±0.91%), and was retained there for >48 h (ID/g at 48 h: 2.17±0.53 %)." (PMID 24932259, 2014). "To rule out this compounding factor and help establish a role for a host-derived immune response, we determined TLR5 mRNA expression in the tumor lines we use throughout this study." (PMID 24454895, 2014). "Consistent with the RT-PCR results, immunohistochemistry staining showed that the expression of TLR5 was strongly localized among the tumor cells than the normal liver cells." (PMID 24932259, 2014). "In another microarray study on PBMC from NSCLC patients, significant elevation in gene expression levels for TLR5, 6, 7, 8, and 10 was found after surgery as compared to that before tumor removal." (PMID 23451142, 2013). "Flagellin targets TLR5, with downstream signaling pathways interacting with LPS-induced antitumor mechanisms, leading to the secretion of anti-tumor effectors and an enhanced tumor suppressive effect." (PMID 40528960, 2025). "Furthermore, TLR5 agonists demonstrated robust anti-tumor actions in tumor models, including breast, colon cancer, and melanoma." (PMID 38630304, 2024). "Importantly, combination therapy with the TLR5 agonist and anti-PD-1 further enhanced the suppressive effect on tumor growth." (PMID 38630304, 2024). "Furthermore, eliminating skin microbiota prevented tumor development, primarily by dismantling several key innate immune sensors, including TLR5, with inflammation as a pivotal correlate of tumorigenesis." (PMID 38617537, 2024). "This leads to the activation of CD8 T cells and enhanced tumor invasion via TLR5 agonists." (PMID 38630304, 2024). "This supports the notion that TLR5 agonists augment the anti-tumor efficacy of anti-PD-1." (PMID 38630304, 2024). "In essence, TLR5 acts in synergy with anti-PD-1 to suppress tumor growth." (PMID 38630304, 2024). "Thus, on day 26 after tumor implantation, we isolated spleens, LNs, and tumors to scrutinize the changes in PD-L1 expression in response to TLR5 agonists." (PMID 38630304, 2024). "Finally, the importance of TLR5 in mediating anti-tumor responses is being explored, with evidence that TLR5 agonists enhance anti-tumor immunity and overcome resistance to immune checkpoint therapy." (PMID 38903515, 2024). "However, reconstitution with bacteria from PDAC hosts leads to the activation of select TLRs (TLR2 and TLR5) in macrophages which contributes to PDAC tumor growth and innate and adaptive immune suppression." (PMID 37588093, 2023). "In addition, an association emerged between a low TLR5 immunoexpression and a lower CD3–CD8 tumor–stroma index (p = 0.003; chi-square test) alongside a weak positive correlation (rs = 0.203; p < 0.001)." (PMID 36649244, 2023). "However, TLR5 agonists acted as organ-specific immunoadjuvants and enabled efficient anti-tumor vaccination by stimulating the NK-DCs-CD8+ T cell axis." (PMID 37191444, 2023). "Furthermore, TLR5-dependent commensal microbiota drives the malignant progression of tumors by increasing IL-6 levels and depletion of the commensal bacteria abrogates TLR5-dependent tumor progression." (PMID 37191444, 2023). "We tested whether TLR5 host receptors are necessary to elicit the anti-tumor response observed in mice treated with CBLB505 in combination with ICT treatments)." (PMID 36635337, 2023). "The activation of TLR5 by bacterial flagellin can induce anti-tumor effects in cancers." (PMID 37628585, 2023). "TLR5, 7, 8, and 9 correlate with better clinical outcomes (high immune cell marker expression and/or longer survival), while TLR4, 7, and 9 are associated with poorer outcomes (advanced tumor stage, poor differenciation, and shorter survival)." (PMID 36479129, 2022). "Treatment with antibiotics inhibits tumor formation in a TLR-5 dependent manner." (PMID 33296049, 2021).
tumor (continued). "TLR5 recognition of flagellin-expressing commensals may favor systemic tumor -promoting inflammation and malignant progression of BC." (PMID 33963313, 2021). "TLR5 agonists have been tested in anti-tumour immunotherapy." (PMID 33499143, 2021). "In OTSCC, a higher TLR-5 expression correlated with lower tumour grade (p = 0.039)." (PMID 33008143, 2020). "On the other hand, TLR5 signalling was found to have anti-tumor effects in NSCLC cells." (PMID 32856858, 2020). "An adenovirus-based tumor-specific delivery vector, called Mobilan, drives the expression of the TLR5 signaling cassette, which is composed of salmonella flagellin and humanTLR5, which is similar in structure to the clinical-stage TLR5 agonist entolimod." (PMID 33469538, 2020). "The results revealed that TLR5+ tumour had the highest T/NT ratio at the 48 hours." (PMID 31576678, 2019). "Our results supply a new strategy for TLR5‐positive tumour monitoring." (PMID 31576678, 2019). "Radioactivities in tumour tissues were positively related with TLR5 expression." (PMID 31576678, 2019). "TLR5 activation via flagellin significantly reduced CRC tumor xenografts in size indicating high immune response which could be utilized as potential immunotherapy." (PMID 31835892, 2019). "Our results suggested that downregulation of TLR5 in TNBC increased tumor invasiveness and EMT expression via TRAF6 and SOX2 pathway and TLR5 could serve as a prognostic and monitoring indicator for TLR5-positive tumors." (PMID 31852883, 2019). "Our results indicated that 125I‐antiTLR5 mAb was an ideal agent for non‐invasive imaging of TLR5+ tumours; TLR5 may be as a novel molecular target for TNBC non‐invasive diagnosis." (PMID 31576678, 2019). "At 48 h, the T/L (tumor to liver), T/K (tumor to kidney), and T/B (tumor to blood) ratios were significantly higher for the TLR5+ 4T1 tumor than for the TLR5− 4T1 tumor (1.70 ± 0.18 vs. 0.24 ± 0.02, 1.68 ± 0.28 vs. 0.24 ± 0.04, and 1.73 ± 0.12 vs. 0.25 ± 0.02, respectively; P < 0.01 for all)." (PMID 31852883, 2019). "In cervical neoplasias, TLR5 is thought to promote tumor progression." (PMID 31314777, 2019). "Cancer cell proliferation and tumor growth are inhibited by TLR5 signaling, but the underlying mechanism has not been fully elucidated." (PMID 31852883, 2019). "Interestingly, TLR4 and TLR5 protein expressions were also observed in tumor cell nuclei, as observed in the immunofluorescence preparations of the GBM cell lineages." (PMID 29912993, 2018). "Similar to the staining pattern in tumor cells, TLR5 positivity was detected in neuron nuclei." (PMID 29912993, 2018). "Interestingly, TLR4 and TLR5 positivity were detected in the tumor cell nuclei by immunofluorescence in cell lineages and by immunohistochemistry in tumor specimens." (PMID 29912993, 2018). "TLR5 agonists inhibit the function or number of Treg cells to suppress tumor growth." (PMID 29268708, 2017). "Indeed, rE7mFliC induced E7-specific T cell responses and anti-tumor efficacies that were similar to those of rE7m, which was unable to induce TLR5 signaling." (PMID 27063435, 2016). "Here, we demonstrated that NLRC4 contributes to the induction of anti-tumor immunity and that TLR5 might play a role transporting flagellin fusion antigens into cells to activate cytosolic NLRC4 inflammasome signaling." (PMID 27063435, 2016). "Activation of TLR5 by Salmonella flagellin stimulates cytotoxic lymphocyte-mediated tumor immunity." (PMID 27145267, 2016). "In tumor-bearing individuals, through interactions between the microbiome and TLR5+ cells that occur at places of bacterial colonization, TLR5 competence drives systemic IL-6 up-regulation, while deficiencies in TLR5 signaling are associated with higher circulating levels of IL-17." (PMID 25897427, 2015). "However, recent studies demonstrated that systemic activation of TLR5 in several syngeneic tumor models decreased tumor burden while significantly improving normal cell survival." (PMID 26220208, 2015).